IGLV6-57 (immunoglobulin lambda variable 6-57)
Description:
V region of the variable domain of immunoglobulin light chains that participates in the antigen recognition. Immunoglobulins, also known as antibodies, are membrane-bound or secreted glycoproteins produced by B lymphocytes. In the recognition phase of humoral immunity, the membrane-bound immunoglobulins serve as receptors which, upon binding of a specific antigen, trigger the clonal expansion and differentiation of B lymphocytes into immunoglobulins-secreting plasma cells. Secreted immunoglobulins mediate the effector phase of humoral immunity, which results in the elimination of bound antigens. The antigen binding site is formed by the variable domain of one heavy chain, together with that of its associated light chain. Thus, each immunoglobulin has two antigen binding sites with remarkable affinity for a particular antigen. The variable domains are assembled by a process called V-(D)-J rearrangement and can then be subjected to somatic hypermutations which, after exposure to antigen and selection, allow affinity maturation for a particular antigen.
Synonyms: IGLV657; V1-22
Tractability: Small molecule: a high-quality ligand is known. Antibody: its Gene Ontology location is reachable by antibodies, with high confidence; UniProt places it where antibodies can reach, with medium confidence; UniProt predicts a signal peptide or a membrane-spanning region. PROTAC: a small molecule that binds it is known.
Gene: Immunoglobulin variable (V) gene on chromosome 22 (22,195,799 to 22,196,276, forward strand). Ensembl gene ENSG00000211640.
Subcellular location: Secreted; Cell membrane
Pathways (Reactome):
Immune System: Antigen activates B Cell Receptor (BCR) leading to generation of second messengers; CD22 mediated BCR regulation; Classical antibody-mediated complement activation; FCERI mediated Ca+2 mobilization; FCERI mediated MAPK activation; FCERI mediated NF-kB activation; FCGR activation; Fc epsilon receptor (FCERI) signaling; Immunoregulatory interactions between a Lymphoid and a non-Lymphoid cell; Initial triggering of complement; Regulation of Complement cascade; Regulation of actin dynamics for phagocytic cup formation; Role of LAT2/NTAL/LAB on calcium mobilization; Role of phospholipids in phagocytosis
Disease: FCGR3A-mediated IL10 synthesis; FCGR3A-mediated phagocytosis; Potential therapeutics for SARS
Hemostasis: Cell surface interactions at the vascular wall
Vesicle-mediated transport: Scavenging of heme from plasma
Gene Ontology:
Molecular function: protein binding; antigen binding
Biological process: immune response
Cellular component: extracellular region; immunoglobulin complex; plasma membrane
Homologues: Orthologues: rat AABR07034730.2 (63% identical), rat AABR07034730.3 (61% identical), rat AC109901.2 (53% identical). Paralogues in human: IGLV1-40 (69% identical), IGLV1-47 (67% identical), IGLV2-18 (67% identical), IGLV1-44 (66% identical), IGLV1-50 (64% identical), IGLV1-51 (64% identical), IGLV2-11 (64% identical), IGLV2-14 (64% identical), IGLV2-8 (64% identical), IGLV2-23 (63% identical), IGLV1-36 (62% identical), IGLV3-25 (59% identical), and 81 more.
Diseases named in the same sentence as IGLV6-57 in open-access papers:
IGLV6-57 is named in the same sentence as 6 diseases in open-access papers, as found by Europe PMC text mining. Sharing a sentence is not in itself a finding about the gene and the disease. The quoted sentences say what the papers report.
AL amyloidosis (4 papers, 2021 to 2026). AL Amyloidosis is a plasma cell disorder characterized by the aggregation and deposition of insoluble amyloid fibrils derived from misfolding of monoclonal immunoglobulin light chains usually produced by a plasma cell tumor. "Additional protein sequence BLAST analysis and alignment show that a similar terminal sequence NFMLTQPHSVSESPG comes from the germline gene of a human immunoglobulin lambda variable 6-57 (IGLV6-57), which is linked to AL amyloidosis." (PMID 37753973, 2023). "IGLV6-57 is the most frequently observed precursor gene in AL amyloidosis." (PMID 39598451, 2024). "LCs derived from the IGLV6-57 gene, which is over-represented in AL amyloidosis, were studied." (PMID 34208058, 2021). "As in our prior study, our controls were two non-amyloidogenic λ LCs: MM, originally identified in a patient with multiple myeloma but without amyloid deposition; and GL, the protein with the precursor germline sequence from which the AL and MM sequences are derived, IGLV6-57." (PMID 41542593, 2026).
amyloidosis (1 paper, 2023). A disorder characterized by the localized or diffuse accumulation of amyloid protein in various anatomic sites. "Eight of 705 (1.1%) clones were derived from IGLV6-57 and one of these sequences (MMRF127938) was reported to have amyloidosis." (PMID 37143670, 2023).
colon cancer (1 paper, 2023). "In addition, expression levels of IGKV1-6, IGLV6-57, and CCL28 were higher in colon cancer, while VIP and FABP4 were more biased to be expressed in high-risk group." (PMID 36890467, 2023).
colorectal cancer (1 paper, 2022). A primary or metastatic malignant neoplasm that affects the colon or rectum. "An article on prognostic markers of colorectal cancer identified IGLV6-57 as a core risk gene in the risk model." (PMID 36581948, 2022).
IGLV6-57 also shares sentences with these, for which no sentence is quoted: tumor (2 papers); multiple myeloma (1).